IL18 (interleukin 18)
Diseases named in the same sentence as IL18 in open-access papers (continued):
Sharing a sentence is not in itself a finding about the gene and the disease.
bone metabolism disorders (1 paper, 2024). "Proinflammatory cytokines, including TNFα, IL6, IL18, IL17, and CRP appear to activate osteoclasts and osteoblasts, leading to bone metabolism disorders." (PMID 38272859, 2024).
Bovine mastitis (1 paper, 2023). INFLAMMATION of the UDDER in cows. "Zophobas morio (Z. morio) hemolymph can decrease the levels of NLRP3, caspase-1 and NLRP6 and inhibit the secretion of IL-1β and IL-18, thereby attenuating E. coli- or Staphylococcus simulans (S. simulans)-induced pyroptosis; thus, it can be a new therapeutic candidate for bovine mastitis." (PMID 37845761, 2023).
bubonic plague (1 paper, 2016). A plague in which the bacteria have infected the lymphatic system. "We have reported that deletion of both YopM and YopJ in a fully virulent Y. pestis KIM1001 strain implicates increased IL-1β and IL-18 in vivo, and leads to significant attenuation following subcutaneous (s.c.)infection mimicking bubonic plague." (PMID 27911947, 2016).
Burkitt lymphoma (1 paper, 2024). A rare form of malignant mature B-cell non-Hodgkin lymphoma. "After confirming that the production of IL-18 by CAR-T cells enhanced the antitumoral effect against a Burkitt lymphoma model, we wanted to validate the use of iTRUCK19.18 cells in a clinically relevant setting." (PMID 39640015, 2024).
C. perfringens infection (1 paper, 2023). "Post- C. perfringens infection, there was a significant increase in intestinal IL-13 (p ≤ 0.001) and IL-18 (p ≤ 0.05) expression in both rL. lactis treated only and rL. lactis treated and subsequently C. perfringens infected chickens compared to control chickens." (PMID 38164397, 2023).
carcinoid tumor (1 paper, 2021). A slow growing neuroendocrine tumor, composed of uniform, round, or polygonal cells having monotonous, centrally located nuclei and small nucleoli, infrequent mitoses, and no necrosis. "With regard to somatostatin analogs and interferon, in 36 patients with metastatic or unresectable carcinoid tumors, treatment with PEG interferon + depot Octreotide was associated with a significant increase in plasma Interleukin 18 (IL-18) and a significant reduction in plasma bFGF." (PMID 34367064, 2021).
cerebral artery occlusion (1 paper, 2010). "In the present study, we compared infarct size in IL-18 knock-out and wild-type mice 24 hours and 48 hours after 1-hour transient middle cerebral artery occlusion (tMCAO)." (PMID 20150990, 2010).
Cerebral atrophy (1 paper, 2025). Atrophy (wasting, decrease in size of cells or tissue) affecting the cerebrum. "The plasma inflammatory markers centered on neutrophils—MMP-9 and IL-18—interact with various risk factors (age, gender, DMTS, DWMH, cerebral atrophy) and contribute to the development of PSCI." (PMID 40821836, 2025).
cerebral small vessel disease (1 paper, 2020). Cerebral small vessel disease is the term currently used to pathological processes that affect the brain parenchymal circulation (arterioles, capillaries, and veins). "We also show that this composite measure of inflammation is associated with increases in DTI free water, further implicating an IL-18-centered inflammatory network in the disease process underlying cerebral small vessel disease." (PMID 31978079, 2020). "We sought to identify whether an interconnected network of inflammatory biomarkers centered on IL-18 and all previously associated with white matter lesions could detect overt and antecedent white matter changes in two populations at risk for cerebral small vessel disease." (PMID 31978079, 2020).
cervical (1 paper, 2023). "Accordingly, the rs10754558 G allele may alter the function of NLRP3, thereby influencing IL-1β and IL-18 secretion in a manner that enhances inflammatory cascade activity and drives pathological changes conducive to cervical oncogenesis." (PMID 37885032, 2023).
Chlamydia infection (1 paper, 2021). "Since cellular immunity is a key component of the protective immune response following Chlamydia infection, we evaluated the magnitude of Th1 (IFN-γ, IL-2, IL-12, IL-18), Th2 (IL-4) and anti-inflammatory (IL-10) cytokines (Expt." (PMID 34001988, 2021).
chlamydial infection (1 paper, 2021). "The secretion of IFN-γ is not only regulated by IL-12, IL-18, IL-10, and other cytokines after chlamydial infection, but is also enhanced through a positive feedback mechanism." (PMID 34093528, 2021). "IL-18 and IL-33 participate in immunologic injury induced by chlamydial infection, although the precise mechanisms in removing chlamydial are still unknown." (PMID 34093528, 2021). "It is reported that IL-18 is the only member of the IL-1 family that can induce T, B and NK cells to produce IFN-γ, which is responsible to controlling chlamydial infection." (PMID 34093528, 2021). "Thus, it is speculated that IL-18 may not be necessary for the clearance of chlamydial infection." (PMID 34093528, 2021).
cholangiocarcinoma (1 paper, 2024). A carcinoma that arises from the intrahepatic biliary tree (intrahepatic cholangiocarcinoma) or from the junction, or adjacent to the junction, of the right and left hepatic ducts (hilar cholangiocarcinoma). "Also, IL-15 and IL-18 stimulated cells contained cytotoxicity against cholangiocarcinoma cells, suggesting that stimulated Vγ9Vδ2 T cells may provide a feasible therapy for cholangiocarcinoma." (PMID 38221530, 2024).
cholangitis (1 paper, 2022). An acute or chronic inflammatory process affecting the biliary tract. "In p40−/−IL-2Rα−/− mice, deletion of IL-18 has no remarkable effect on disease progression, while deletion of IL-21 indicates that it is necessary for AMA production but independent of liver inflammation and cholangitis." (PMID 35300072, 2022).
cholelithiasis (1 paper, 2023). The presence of crystallized deposits forming in the gallbladder or biliary tree, primarily composed of cholesterol, bilirubin, and bile. "In addition, the ELISA results showed that TNF-α, IL-1β, and IL-18 expression was markedly up-regulated in the gallbladder tissues of mice with cholelithiasis compared with the normal control mice." (PMID 37641009, 2023).
chromoblastomycosis (1 paper, 2025). "Our results show a significant decrease of Th1 cells in the organs of C57BL/6 KO mice suggests that IL-18 is implicated in the induction of a Th1 response and control of chromoblastomycosis." (PMID 40315193, 2025). "In conclusion, the present data demonstrate, for the first time, that the inflammasome is activated and that NLRP3 and caspase-1 mediated the F. pedrosoi-induced production of IL-18, which promotes the Th-1-mediated immune response during chromoblastomycosis." (PMID 40315193, 2025). "Moreover, IL-18 plays a crucial role in activating Th1 cells and controlling fungal loads during chromoblastomycosis." (PMID 40315193, 2025). "Moreover, we showed that IL-18 is required to activate the Th1 response and control fungal loads during chromoblastomycosis." (PMID 40315193, 2025). "Therefore, we suggest that the IL-18−/− mice were susceptible to chromoblastomycosis because they exhibited reduced Th1 (and not Th17) immunity." (PMID 40315193, 2025). "However, there is no data on the importance of IL-18 in activating Th cells during chromoblastomycosis." (PMID 40315193, 2025).
chronic leukemia (1 paper, 2015). A slowly progressing leukemia characterized by a clonal (malignant) proliferation of maturing and mature myeloid cells or mature lymphocytes. "Significant associations were detected between the IL-18 rs187238(G/C) polymorphism and chronic leukemia." (PMID 26376814, 2015). "IL-18 gene promoter rs187238(G/C) polymorphism is associated with chronic leukemia in the Turkish population." (PMID 26376814, 2015).
chronic recurrent multifocal osteomyelitis (1 paper, 2025). "Autoinflammatory phenotypes include chronic recurrent multifocal osteomyelitis (CRMO), juvenile idiopathic arthritis, and intestinal inflammation, which may result from enhanced monocyte responses to TLR ligands and increased secretion of proinflammatory factors (e.g., IL-8, IL-18)." (PMID 40755762, 2025).
chronic spontaneous urticaria (1 paper, 2013). "Overproduction of IL-18 expression was described in some adults with chronic spontaneous urticaria but not in all studies." (PMID 24490166, 2013).
Chylothorax (1 paper, 2022). The presence of chyle in the thoracic cavity. "Patients with serum IL-18 levels less than or equal to 45.005 pg/ml may have a higher risk of disease progression, while serum PD-1 levels less than or equal to 21.350 pg/ml indicate a higher risk of pneumothorax and/or chylothorax." (PMID 35300340, 2022).
Cm (1 paper, 2025). "Consistently, our transcriptomic analysis shows significant downregulation of genes involved in the IL-12 and IL-18 signaling pathways in DCs from NK cell-depleted mice with Cm infection." (PMID 40332391, 2025).
coccidiosis (1 paper, 2023). A parasitic infection caused by Coccidia. "IL-18 has been used as an adjuvant in recombinant bacterial vaccines against porcine circovirus type 2 in pigs and coccidiosis in chickens." (PMID 38140192, 2023).
corneal diseases (1 paper, 2025). "In other corneal diseases, including DED and alkali burn injury, NLRP3 activation has been shown to drive inflammation through IL-1β and IL-18 production." (PMID 40943162, 2025).
coronary thrombosis (1 paper, 2019). Coagulation of blood in any of the coronary vessels. "IL-18, known as IFN-γ inducing factor, is in charge of the up-regulation of other inflammatory cytokines and adhesion molecules and contributes to the weakening of the extracellular matrix of plaque, which is the primary cause of coronary thrombosis." (PMID 31419967, 2019).
Cushing syndrome (1 paper, 2016). Cushing's syndrome (CS) encompasses a group of hormonal disorders caused by prolonged and high exposure levels to glucocorticoids that can be of either endogenous (adrenal cortex production) or exogenous (iatrogenic) origin. "There are indirect studies where it is reported that Cushing Syndrome patients, which have a high risk of osteoporotic fractures have high IL-18 serum levels." (PMID 27649785, 2016).
cutaneous leishmaniasis (1 paper, 2025). Leishmaniasis affecting the skin. "Inflammasome markers IL‐1β+ and IL‐18+ were significantly higher in cutaneous leishmaniasis (p < 0.05)." (PMID 40947759, 2025).
demyelinating disease (1 paper, 2022). A broad group of disorders that affect the myelin sheaths that cover the neurons. "Thus intervention to inhibit IL-18 may be a future target for demyelinating diseases." (PMID 36160384, 2022).
dental caries (1 paper, 2020). The decay of a tooth, in which it becomes softened, discolored, and/or porous. "IL-18 is also a pro-inflammatory cytokine, and its secretion is strongly induced in pulp inflammation caused by dental caries." (PMID 33105546, 2020).
diabetic ketoacidosis (1 paper, 2024). The metabolic condition resulted from uncontrolled diabetes mellitus, in which the shift of acid-base status of the body toward the acid side because of loss of base or retention of acids other than carbonic acid is accompanied by the accumulation of ketone bodies in body tissues and fluids. "Accordingly, in children suffering from diabetic ketoacidosis, IL-18 has been shown to be positively associated with their acidotic state." (PMID 38338685, 2024).
diffuse large B-cell lymphoma (1 paper, 2019). "There is a growing body of evidence supporting the utility of pretreatment serum levels of sIL-2R and IL-18 as prognostic factors in diffuse large B-cell lymphoma patients." (PMID 31608153, 2019).
disc degeneration (1 paper, 2020). "Compared with NPCs from patients with grade IV disc degeneration, the expression of cleaved CASP1, IL-1β and IL-18 was higher in NPCs from patients with grade V disc degeneration." (PMID 32320383, 2020).
disseminated candidiasis (1 paper, 2024). Systemic candidiasis occurs when Candida yeast enters the bloodstream and may spread (becoming disseminated candidiasis) to other organs, including the central nervous system, kidneys, liver, bones, muscles, joints, spleen, or eyes. "Previous studies have found that IL-18 deficiency results in increased mortality and fungal burden during systemic C. neoformans and C. albicans infection, and supplementation of IL-18 can improve outcomes in models of disseminated candidiasis (51, –, 54)." (PMID 38619236, 2024).
dyslipidaemia (1 paper, 2018). "Gene-gene interaction was shown between ENHO rs2281997 and IL18 rs360719 with respect to dyslipidaemia by K/DOQI and IL12A rs568408 with respect to atherogenic dyslipidaemia." (PMID 30413149, 2018). "Therefore, we analysed gene-gene epistatic interactions between ENHO SNPs (rs2281997, rs72735260) and Th1 cell cytokine gene SNPs (IL12A rs568408, IL12B rs3212227, and IL18 rs360719) with respect to both types of dyslipidaemia." (PMID 30413149, 2018).
End Stage Liver Disease (1 paper, 2011). Final stage of a liver disease when the liver failure is irreversible and LIVER TRANSPLANTATION is needed. "IL-18 promoter genotyping was performed by the snapshot technique in 125 patients with HBV-related end-stage liver disease (ESLD) receiving LT in our center from 2004 to 2008." (PMID 22087180, 2011).
endophthalmitis (1 paper, 2025). An infectious process affecting the internal structures of the eye. "The opposite direction of the correlation between IL-10 and IL-18 in endophthalmitis and control groups is interesting, as IL-10 is known to be a regulator of IL-18 signalling, and subsequent IFN-γ induction by NK cells." (PMID 40563988, 2025). "Interestingly, IL-18/IL-10 was also significantly correlated in both groups; however, the correlation was negative in the endophthalmitis group and positive in the controls." (PMID 40563988, 2025).
eosinophilic granulomatosis with polyangiitis (1 paper, 2024). Eosinophilic granulomatosis with polyangiitis (EGPA), previously known as Churg-Strauss syndrome, is a systemic vasculitis of small-to medium vessels, characterized by asthma, transient pulmonary infiltrates, and hypereosinophilia. "Eosinophilic granulomatosis with polyangiitis—typically associated with abnormal immune activation—may involve abnormal expression of IL‐18 in its pathogenesis." (PMID 39188114, 2024).
Erythema (1 paper, 2008). Redness of the skin, caused by hyperemia of the capillaries in the lower layers of the skin. "Clinical appearance and examination of weight curves revealed that IL-18 treated mice had more significant manifestations of GVHD as indicated by lethargy, hunched posture, generalized erythema, and a progressive reduction in mean weights from pretransplant levels (data not shown)." (PMID 18818761, 2008).
erythroderma (1 paper, 2023). "The findings showed an atypical expression of IL-1B and IL-18 that was verified in the skin of SS patients but not in the EI group, indicating that it may not be related to an erythroderma condition." (PMID 36902104, 2023).
extra pulmonary tuberculosis (1 paper, 2021). "A case control study was conducted to investigate the polymorphism at IL-18-607, -137 and INF-γ+874 by sequence specific primer-polymerase chain reaction (SSP- PCR) in 105 patients with pulmonary and extra pulmonary tuberculosis and 106 controls." (PMID 33412574, 2021).
eye inflammation (1 paper, 2023). "These inflammatory mediators act synergistically with IL-1β and IL-18 to promote the recruitment of inflammatory immune cells from the bloodstream to the site of eye inflammation." (PMID 37759549, 2023).
female infertility (1 paper, 2024). Diminished or absent ability of a female to achieve conception. "The role of genetic predispositions to MDD in influencing genetically predicted IL-18 levels, and subsequently, female infertility, was highlighted by our study, offering insights into the complex interplay between mental health and reproductive biology." (PMID 40226698, 2024). "Mediation analysis indicated that genetically predicted IL-18 levels partially mediated the impact of MDD on female infertility associated with cervical, vaginal, other or unspecified origin, accounting for up to 14.61% of this effect." (PMID 40226698, 2024). "Further exploration of different types of female infertility revealed that IL-18 partially mediated the effect of MDD on female infertility associated with cervical, vaginal, other or unspecified origin." (PMID 40226698, 2024). "Understanding how IL-18 influences this relationship may provide valuable insights into the underlying mechanisms and offer new avenues for addressing female infertility in individuals affected by MDD." (PMID 40226698, 2024). "In conclusion, our study suggests a potential role of IL-18 as a partial mediator in the association between MDD and female infertility, particularly in cases with cervical, vaginal, and other or unspecified origin." (PMID 40226698, 2024). "Our study is the first MR investigation exploring IL-18 as a partial mediator in the association between MDD and female infertility." (PMID 40226698, 2024). "Notably, IL-18 levels were only found to be altered in female infertility, suggesting the influence of sex-specific factors." (PMID 40226698, 2024). "Notably, genetically predicted IL-18 levels demonstrated a protective effect against female infertility (odds ratio (OR): 0.92; 95% CI: 0.86–0.98; P = 1.17 × 10−2)." (PMID 40226698, 2024). "Finally, the mechanisms underlying the association between MDD, IL-18, and female infertility were not fully elucidated." (PMID 40226698, 2024). "The mediating role of IL-18 lies in its potential to act as a biological bridge between MDD and female infertility." (PMID 40226698, 2024).
fibroblast disorder (1 paper, 2017). "Further investigations on the mechanism underlying caspase-1-regulated pyroptosis and IL-18/IL-1β-regulated fibroblast disorder are required to elucidate the function of NLRP3 inflammasome in DCM." (PMID 28790925, 2017).
focal epilepsy (1 paper, 2021). A seizure caused by a localized disorder. "While increased IL-18 protein levels have been observed in serum of epileptic patients compared with healthy controls, another study found a slight decrease of IL-18 in mesial TLE and focal epilepsy patients." (PMID 34572093, 2021).
food allergy (1 paper, 2015). Gastrointestinal disturbances, skin eruptions, or shock due to allergic reactions to allergens in food. "These effector cells then release a collection of Th2 cytokines (IL-4, IL-5, IL-9, IL-13, IL-15 and IL-18) that are organized in the intestinal immune system for prompting food allergy or anaphylactic immune responses upon successive exposure to the antigen." (PMID 27840774, 2015). "These effector cells, through exposure to an array of Th2 cytokines (IL-4, IL-5, IL-9, IL-13, IL-15 and IL-18) in the intestinal immune system, are primed for food allergy or anaphylactic reactions upon subsequent antigen exposure." (PMID 27840774, 2015).
fulminant viral hepatitis (1 paper, 2025). Fulminant viral hepatitis is a rapid and severe impairment of liver functions (acute liver failure) with hepatic encephalopathy developing less than 8 weeks after the onset of jaundice, secondary to viral hepatitis mainly due to HBV, but also to HAV. "A previous report described an inherited deficiency of IL-18BP, a soluble antagonist of IL-18, in an Algerian patient who died of fulminant viral hepatitis (FVH) A. We report here an Egyptian family with two siblings who died from FVH following infection with hepatitis A virus." (PMID 41334112, 2025).